CST11 (cystatin 11)
Description:
Has antibacterial activity against the Gram-negative bacteria E.coli. May play a role in sperm maturation and fertilization.
Synonyms: CST8L; dJ322G13.6; CTES2; SC13
Tractability: Antibody: UniProt places it where antibodies can reach, with high confidence; UniProt predicts a signal peptide or a membrane-spanning region; its Gene Ontology location is reachable by antibodies, with medium confidence.
Gene: Protein-coding gene on chromosome 20 (23,450,403 to 23,453,210, reverse strand). Ensembl gene ENSG00000125831.
Subcellular location: Secreted
Gene Ontology:
Molecular function: cysteine-type endopeptidase inhibitor activity
Biological process: defense response to Gram-negative bacterium; killing of cells of another organism; androgen receptor signaling pathway
Cellular component: cytoplasm; nucleus; sperm flagellum; sperm head; extracellular region
Genetic constraint (gnomAD): Loss-of-function variants: 11 observed, 12.84 expected, observed/expected ratio (o/e) 0.86, 90% interval 0.54 to 1.41. The upper end of that interval is the gene's LOEUF score, 1.41, which puts it in group 5 of 6, group 1 being the genes least tolerant of losing a copy. Missense variants: 174 observed, 162.23 expected, observed/expected ratio (o/e) 1.07, 90% interval 0.95 to 1.22. Synonymous variants: 64 observed, 60.53 expected, observed/expected ratio (o/e) 1.06, 90% interval 0.86 to 1.3.
Homologues: Orthologues: chimpanzee CST11 (97% identical), macaque CST11 (87% identical), dog CST11 (62% identical), mouse Cst11 (54% identical), pig CST11 (52% identical), rat Cst11 (50% identical), guinea pig Cst11 (48% identical), zebrafish si:busm1-57f23.1 (20% identical), Caenorhabditis elegans cpi-2 (16% identical), Caenorhabditis elegans cpi-1 (14% identical), Caenorhabditis elegans K08B4.7 (7% identical). Paralogues in human: CST8 (33% identical), CST6 (29% identical), CST3 (28% identical), CSTL1 (27% identical), CST5 (26% identical), CST1 (25% identical), CST2 (25% identical), CST4 (25% identical), CST9L (24% identical), CST7 (20% identical), CST9 (16% identical).
Diseases named in the same sentence as CST11 in open-access papers:
CST11 is named in the same sentence as 4 diseases in open-access papers, as found by Europe PMC text mining. Sharing a sentence is not in itself a finding about the gene and the disease. The quoted sentences say what the papers report.
male infertility (1 paper, 2024). The inability of the male to effect fertilization of an ovum after a specified period of unprotected intercourse. "Mice lacking 8 cystatin genes (Cstl1, Cst11, Cstdc1, Cst12, Cst8, Cst13, Cst9, and Cstdc2) on chromosome 2 possess defective sperm maturation and male infertility." (PMID 38169386, 2024).
CST11 also shares sentences with these, for which no sentence is quoted: cervical cancer (1 paper); endometriosis (1); keloid (1).